ATM (ATM serine/threonine kinase)
Diseases named in the same sentence as ATM in open-access papers (continued):
Sharing a sentence is not in itself a finding about the gene and the disease.
cancer (continued). "ATM-regulated PKM2-mediated activation of CtIP may represent a means for highly proliferative cancer cells to accentuate this repair mechanism and may be one of the important mechanisms through which these cells manage increased oxidative stress." (PMID 30297868, 2018). "Why does defective ATM signalling caused by C9orf72 expansions not predispose to cancer or immunodeficiency?" (PMID 29584802, 2018). "Moreover, this correlation with ATM was abrogated when analyzing ATM mutant breast or gastric cancer patients, suggesting ATM plays a functional role in CTL recruitment and is not merely correlational." (PMID 29615613, 2018). "Moreover, NAC prevented phosphorylation of ATM, providing further support of an oxidative DNA damage driving the anti-cancer mechanism." (PMID 29855474, 2018). "More studies are urgently needed to ascertain the molecular mechanisms through which this panel of cytosolic functions of ATM could modulate cancer development and therapy." (PMID 29616191, 2018). "As we found levels of the cytokines CCL5, CXCL9, CXCL10, and IL16 to indicate high CTL score across multiple cancers, we hypothesized that ATM in its role as a signal transducer may be promoting the transcription of these cytokines." (PMID 29615613, 2018). "Altogether, this suggests an interplay between ATM and c-myc in cancer metabolism." (PMID 29238697, 2017). "In this study, we provided the compelling evidence that Cdc7-Dbf4 interacts with HCLK2-HSP90-Mre11 complex and phosphorylates HSP90-S164 to enhance ATR/ATM checkpoint signaling, HR DNA repair, and checkpoint recovery, which enhances replication stress tolerance for the survival of cancer cells." (PMID 29209046, 2017). "Together, these data demonstrate the importance of ATM signaling to induce senescence and suggest that ATM’s role in modulating senescence status offers the possibility of a future therapeutic target in the fields of both aging and cancer." (PMID 29238697, 2017). "The hypermethylation of the BRCA1 promoter or the loss of function of other genes as ATM, CHEK2, RAD51, BRIP1, and PALB2 belonging at DNA repair machinery, define a specific phenotype with features and behavior similar to BRCA-related cancers, defined as “BRCAness”." (PMID 28055979, 2017). "For this reason, ATM inhibitors have been developed for use in cancer therapy." (PMID 29348882, 2017). "The PARP and ATM/ATR inhibitors are currently the most promising novel agents undergoing investigation in these solid tumours, as DDR seems to be affected in most of these germline-mutated or BRCA-like cancers." (PMID 29069866, 2017). "The efficacy of Ataxia-Telangiectasia Mutated (ATM) kinase signalling inhibition in cancer therapy is tempered by the identification of new emerging functions of ATM, which suggests that the role of this protein in cancer progression is complex." (PMID 28423511, 2017). "Multiple lines of evidence suggest that DNA-PK may be essential for cancer cell survival when ATM is lost." (PMID 29088817, 2017). "Together, these studies have found that cancer cells may be sensitized to DNA damage through inhibition of ATM." (PMID 29238697, 2017).
cancer (continued). "We propose that upregulation of the γH2AX-inducing factor (such as ATM) by MYC in cancer cells might result in persistent formation of γH2AX foci, which serves as a pseudo-positive DSB signal that sustains the activation of DNA-repair machinery." (PMID 28590415, 2017). "ATM (ataxia telangiectasia mutated) belongs to the PI3/PI4-kinase family, is able to form a complex with EGFR, causes phosphorylation of AKT and was suggested as a therapeutic target in cancer." (PMID 28199979, 2017). "Being PARP-1 and ATM both involved in DNA repair mechanisms (BER and HR respectively), the synergic action between these two proteins could explain the PARP inhibitors resistance of cancer cells leading wild type ATM." (PMID 28055979, 2017). "In addition, a phase I clinical trial is currently ongoing with an ATM inhibitor in combination with a PARP inhibitor in advanced cancer patients who are resistant to the standard-of-care." (PMID 29238697, 2017). "Our findings suggest that high SLFN11 and low ATM expression levels predict PARP inhibitor response in PDX models and/or cell lines, whereas standard biomarkers of PARP inhibition defined in other cancer types (mutational burden, Myriad HRD score, and mutations in DDR genes) do not." (PMID 28212573, 2017). "Oligo-Fucoidan impedes etoposide inducing the rapid activation of ATM and its downstream molecules (Chk1 and Chk2), which may enhance chemosensitivity and lead to the reduced chances of cancer stemness and relapse." (PMID 28928376, 2017). "Finally, it has been reported that expression of a recombinant propeptide displaying LOX activity interferes with the DSB repair response in cancer cells by abrogating ATM phosphorylation." (PMID 28701698, 2017). "Moreover, ATM depletion attenuated the phenotypic changes induced by Mael depletion in cancer cells, decreasing PARP cleavage, senescent cell numbers, and ROS production." (PMID 27926513, 2017). "We show that CC-115 sensitized two ATM-proficient cancer cell lines to etoposide treatment, suggesting that inhibition of dsDNA repair pathways by CC-115 may also sensitize tumor to radio- and chemo-therapy that induce DNA damage." (PMID 29088817, 2017). "As such, squalene may be a desirable sensitizer for cancer therapy because it is an endogenous molecule that inhibits ATM with minimal side effects." (PMID 26824362, 2016). "The contribution of ATM/CHK pathway activation to viral replication has begun to be deciphered but its function in HPV-induced cancer development remains unclear, especially because E7 and E6 have important roles in promoting this activation." (PMID 27918748, 2016). "ATM is a tumor suppressor gene that is frequently inactivated in human cancers." (PMID 27304073, 2016). "Accordingly, our study was to explore the possible molecular mechanism mediated by ATM by which LDR protects normal cells but not cancer cells against the damage caused by a subsequent HDR and suggest potential applications in cancer treatment." (PMID 27708248, 2016). "On the other hand, ATM-deficient cancer cells are strongly nononcogene addicted to DNA-PKcs for survival after DNA damage, to such an extent that DNA-PKcs inhibition sensitizes ATM-deficient tumors to genotoxic chemotherapy." (PMID 27821802, 2016). "Therefore, the prospect of using functional data (i.e. MAPK7 activity) will provide a closer view to the MAPK7 - ATM relationship in human cancer." (PMID 27793024, 2016). "The serine/threonine kinase ATM is well known for its involvement in the DNA damage response (DDR) and maintaining genome stability but it has also been implicated in other cancer-relevant processes including cell growth, metabolism and mitochondrial homeostasis." (PMID 27922010, 2016).
cancer (continued). "The similarity between AtmKD/- cells and ATM kinase inhibitor treated Atm+/-(+) cells further suggest that ATM inhibitors, which have recently entered clinical trials, could potentially increase the efficacy of Topo1 inhibitors in ATM+/+ cancers." (PMID 27304073, 2016). "Missense mutations in ATM kinase, a master regulator of DNA damage responses, are found in many cancers, but their impact on ATM function and implications for cancer therapy are largely unknown." (PMID 27304073, 2016). "Therefore, it is possible that the dose of LDR is insufficient to induce the levels of DNA lesions in cancer cells that can activate ATM protein kinase." (PMID 27708248, 2016). "So far, the main mechanisms by which Roc-A inhibits cancer cell proliferation have been shown to be due to inhibition of protein synthesis initiation and induction of Cdc25A degradation by activation of the ATM/ATR check point pathway." (PMID 27340868, 2016). "Although this cancer gene has not previously been reported to be associated with metformin action, there is growing evidence of the role of ATM in glucose metabolism." (PMID 26606753, 2016). "Although ground breaking studies have led to a better and deeper understanding of ataxia telangiectasia mutated (ATM) gene function, no effective therapy is currently available to prevent cancer or progressive neurodegeneration." (PMID 27073845, 2016). "ATM repression by NSE-activating SSOs might be advantageous for cancer treatment by inhibiting the double-strand break signaling pathway and radiosensitization." (PMID 27658045, 2016). "ATM inhibitors sensitize cancer cells to cytotoxic therapy that induces double-strand breaks, including local radiotherapy, an integral part of treatment regimens of many cancer types." (PMID 27658045, 2016). "Similar to the case of PARP and BRCA, Riabinska et. al. observed that cancers with ATM-deficiency are defective in HR and dependent on nonhomologous end joining (NHEJ) for DNA repair and cell survival." (PMID 27686855, 2016). "Moreover, conjugating such specific ATM inhibitors with coupling agents harboring high affinity to cancer cells would result in new therapeutic agents as radiosensitizers." (PMID 27229179, 2016). "Notably, AZD6738 strongly synergizes with cisplatin in an ATM-deficient NSCLC cell line, as has been reported with other ATR kinase inhibitors and other cancer cells previously." (PMID 26517239, 2015). "When interleukin-8 was added to ATM-depleted cancer cells, it rescued their defects in spreading and invasiveness, thereby providing strong evidence that interleukin-8 is a biologically important target of ATM." (PMID 26030852, 2015). "We hypothesize based on our findings that targeting ATM could inhibit IL-8 dependent processes involving tumor progression and metastasis in certain cancers." (PMID 26030852, 2015). "Abnormal expression of ATM and γH2AX has been detected in various cancers with different roles." (PMID 25861265, 2015). "We found that the sensitivity of cancer cells to BO-1055 was increased following a combined treatment with the inhibitors of the DNA damage sensors ATM and ATR kinases, suggesting that both ATR and ATM are important in the repair of BO-1055-induced lesions in different fashions." (PMID 26208482, 2015). "In addition, HDAC inhibition can suppress the ATM signaling pathway, thereby sensitizing cancer cells to DNA damage." (PMID 25759362, 2015). "In addition, the cancer genome atlas (TCGA) database was interrogated for alterations in: 1) ATM, MRE11A, RAD50 and NBN; 2) ATR, ATRIP and TOPBP1; and 3) 15 FA genes." (PMID 26438152, 2015). "Accumulation of H2AX phosphorylation (γH2AX), which could be mediated by ATM, has been detected in various cancers." (PMID 25861265, 2015). "Together, these findings suggest that ATM could be a potential target for anti-cancer therapies, as inhibiting this enzyme would inhibit interleukin-8, and in turn slow the progression and spread of cancer." (PMID 26030852, 2015).
cancer (continued). "Low-ATM levels are associated with increased BMP4 levels and elevated stem cell gene signatures, which have been previously linked to disease outcome in a variety of cancers including colorectal cancer." (PMID 26220524, 2015). "In a treatment-naïve background, elevated γ-H2AX levels might mirror a strategy, namely the activation of the ATM-Chk2 pathway, cancer cells evolved to tolerate endogenous DNA damages arising upon oncogene-induced replication stress." (PMID 26544894, 2015). "ATM inhibition has been proposed as a strategy for cancer treatment." (PMID 26584331, 2015). "Splice-site mutations in the cancer-associated genes RNF31 and ATM also correlated with the skipping of exons harboring these mutations and may lead to a partial deletion of these proteins." (PMID 26109429, 2015). "It is noteworthy that in HepG2 and Bel-7402 cancer cells, Q6 (2.5 μM, 5 μM) under hypoxia for 6 h could activate ATM signaling pathway in a dose-dependent manner." (PMID 26649750, 2015). "We envision that 53BP1 hypo-phosphorylation and ATM inactivation, along with the failure of RIF1 and PTIP foci formation, may emerge as novel indicators for PARPi resistance in BRCA1-mutated cancer patients." (PMID 27462418, 2015). "On the other hand, ATM mediated regulation of signalling cascades could also drive cancer progression." (PMID 26275218, 2015). "Thus, these pathways, including the activity of ATM, were previously thought to only be involved in cancer suppression." (PMID 26030852, 2015). "Importantly, the inhibition of ATM abrogated IL-6's effect on cancer nests formation in the lung of NCI-H446 or A549 cells transferred recipients." (PMID 26528698, 2015). "ATM is a kinase involved in cell cycle control and cancer development." (PMID 26506520, 2015). "Therefore, a better understanding of the network of ATM/ATR-mediated prosurvival pathways in Drosophila ISCs shed insights into not only cancer therapy, but also how stem cell homeostasis is regulated in an aging gut, as shown in the present study." (PMID 26000719, 2015). "Notably, we observed several novel associations between specific cancer types and genes, including RAD51C in AML, ATM in PRAD, PALB2 and EME2 in STAD." (PMID 26689913, 2015). "Moreover ATM pharmacological inhibition has been shown to inhibit AKT-dependent prosurvival signal in cancer cells." (PMID 24681585, 2014). "As ITCH may modulate several proteins clearly involved in cancer initiation, progression and therapy, it will be intriguing to evaluate whether the ATM-ITCH axis may be relevant in cancer as well." (PMID 25594035, 2014). "Mediator of DNA damage checkpoint protein 1 (MDC1) plays an early and core role in Double-Strand Break Repair (DDR) and ataxia telangiectasia-mutated (ATM) mediated response to DNA double-strand breaks (DSBs), and thus involves the pathogenesis of several DNA damage-related diseases such as cancer." (PMID 25198518, 2014). "Interestingly, a role for the DDR and ATM activation in the regulation of cancer stem cell survival has been proposed." (PMID 24681585, 2014). "One additional interesting issue comes from the observation that the modulation of ATM expression and activity by different stimuli may impinge on tumorigenesis and cancer therapy depending on the specific context." (PMID 25594035, 2014). "From the analysis of GBM dataset, we could find functional evidences of four targets including CDKN1A, MTAP, KIT and ATM among top 20 ranked miRNA-mRNA interaction pairs have been reported in GBM cancer." (PMID 25079112, 2014).
cancer (continued). "These key roles in the DDR have ensured that ATM has been a prime candidate for inhibition in cancer treatment and further investigations into synthetic lethality for AT patients may show promise." (PMID 24795863, 2014). "Recently, ATM was found to be activated independently from DNA damage through redox-dependent mechanisms and to participate in diverse signaling pathways involved in metabolic regulation and cancer." (PMID 24568192, 2014). "Incubation of human cancer cell lines with resveratrol was shown to lead to S phase cell cycle arrest or senescence that could be blocked by caffeine (an inhibitor of both ATM and the related ATR protein kinase) or by an ATM-specific inhibitor." (PMID 24933654, 2014). "In this context, targeting ATM seems very useful for killing cancer stem cells in the tumor." (PMID 24681585, 2014). "During the last 15 years, work of many laboratories identified a role for ATM in the modulation of numerous signalling pathways whose deregulation in cancer may promote tumorigenesis and tumor progression." (PMID 24681585, 2014). "In this study we aimed to determine the prevalence of ATM variants among AI cancer patients and compare this to non-AI cancer patients." (PMID 24416720, 2013). "Based on miRNA cancer profiling projects, several ATM-dependent miRNAs merited closer examination." (PMID 23741392, 2013). "However, the association between the ATM IVS 22-77 T>C genetic variant and cancer risk is controversial." (PMID 22276117, 2012). "Pharmacologic inhibition of ATM as a therapeutic strategy to enhance efficacy of DNA-damaging cancer treatments has been proposed, but may involve risks related to facilitation of carcinogenesis." (PMID 23185347, 2012). "For example, ATM is critical for the mitotic checkpoint and its mutation is associated with human cancer, whereas ATR is not." (PMID 23251624, 2012). "Considering the ATM multifunction, it might affect several pathways in the hallmarks and therefore involve diverse mechanisms in different cancer types." (PMID 22276117, 2012). "A premalignant gene expression signature that exhibits reduced ATM expression might be a prerequisite for SATB1 to induce cancer phenotypes." (PMID 23251624, 2012). "The nettle part content differences indicate that different parts could be used for different cancers in ATM." (PMID 22593694, 2012). "However, besides increased radiosensitivity, patients with AT also show increased cancer development, and therefore, prolonged ATM inhibition should be avoided." (PMID 22323184, 2012). "We suggest that repeated injuries over time may need to accumulate in order to manifest gross chromosomal abnormalities and cancers late in the life of a NEK1-deficient animal, as in the life of an ATM-deficient animal." (PMID 21214959, 2011). "We have recently added metformin to the growing list of agents that may have potent cancer-preventive properties by activating the ATM-regulated DDR pathway." (PMID 22170748, 2011). "We recently hypothesized that the unexpected ability of metformin to promote the activation of ATM may be due to the short (24 or 48 h) time courses of most published studies on metformin-induced energetic stress and human cancer cell death in vitro." (PMID 22170748, 2011). "Ataxia Telangiectasia Mutated (ATM) Kinase, which functions as the primary sensor and transducer of DNA damage signal, has been demonstrated to play an important role in the DDR and cancer prevention." (PMID 21980462, 2011).